TMEM14B (transmembrane protein 14B)
Description:
Primate-specific protein involved in cortical expansion and folding in the developing neocortex. May drive neural progenitor proliferation through nuclear translocation of IQGAP1, which in turn promotes G1/S cell cycle transitions.
Synonyms: MGC1223
Tractability: Antibody: UniProt predicts a signal peptide or a membrane-spanning region. PROTAC: ubiquitination databases record sites on it.
Gene: Protein-coding gene on chromosome 6 (10,747,746 to 10,852,753, forward strand). Ensembl gene ENSG00000137210.
Subcellular location: Membrane
Gene Ontology:
Molecular function: identical protein binding; protein binding
Biological process: cerebral cortex development; neural precursor cell proliferation; regulation of G1/S transition of mitotic cell cycle; heme biosynthetic process
Cellular component: mitochondrial membrane; membrane
Genetic constraint (gnomAD): Loss-of-function variants: 8 observed, 14.6 expected, observed/expected ratio (o/e) 0.55, 90% interval 0.32 to 0.99. The upper end of that interval is the gene's LOEUF score, 0.99, which puts it in group 4 of 6, group 1 being the genes least tolerant of losing a copy. Missense variants: 124 observed, 143.15 expected, observed/expected ratio (o/e) 0.87, 90% interval 0.75 to 1.01. Synonymous variants: 40 observed, 51.36 expected, observed/expected ratio (o/e) 0.78, 90% interval 0.6 to 1.01.
Homologues: Orthologues: macaque TMEM14B (89% identical), chimpanzee TMEM14B (88% identical). Paralogues in human: TMEM14C (74% identical), TMEM14A (39% identical).
Diseases named in the same sentence as TMEM14B in open-access papers:
TMEM14B is named in the same sentence as 5 diseases in open-access papers, as found by Europe PMC text mining. Sharing a sentence is not in itself a finding about the gene and the disease. The quoted sentences say what the papers report.
cancer (1 paper, 2022). A tumor composed of atypical neoplastic, often pleomorphic cells that invade other tissues. "There is no record of TMEM14B being linked to NBL and the association of TMEM14B to cancer is not clear; however, other members of the TMEM protein family have been found in some NBL samples." (PMID 36037157, 2022).
TMEM14B also shares sentences with these, for which no sentence is quoted: hepatocellular carcinoma (1 paper); infection (1); Obesity (1); tumor (1).